TNF (tumor necrosis factor)
Diseases named in the same sentence as TNF in open-access papers (continued):
Sharing a sentence is not in itself a finding about the gene and the disease.
cancer (continued). "Consistent with international consensus for cachexia diagnosis, our results demonstrate systemic inflammation in cancer cachectic vs. non-cachectic patients, with increased circulating CRP, IL6, TNFα, IL8, and IL5 levels." (PMID 28288584, 2017). "No major alterations were found between the levels of the pro-inflammatory TNF, IL6, CCL2 and CCL5 and of the anti-inflammatory CD163 in macrophages cultured in the presence of cancer cells, with or without radiation exposure." (PMID 27513864, 2016). "In contrast, treatment of SCC-25 cells with AMP-18 did not inhibit TNF-α induced cleavage of caspase 3 in SCC-25 cells, indicating a different response in these cancer cells." (PMID 27049860, 2016). "The present data showed that, as opposed to in chondrocyte or cancer cells, the mRNA and protein expression of autophagy-related genes, LC3 and Beclin-1, showed no change in response to TNF-α and IL-1β." (PMID 26165348, 2015). "Compared to control group, higher plasma levels of CRP, fibrinogen, IL-6, TNF-α, IL-1β, MMP-9, VEGF, TF antigen, and sP-selectin were observed in cancer patients with and without DVT (P<0.01)." (PMID 26192925, 2015). "MCF7 cells increase STS activity in response to IL-6 and TNFα without alteration in STS mRNA levels, a trait also noted in other cancer cell lines." (PMID 26213785, 2015). "Spontaneous production of cytokines, such as IL-6, TNF-α, Il-1β and VEGF were significantly higher in both groups of cancer patients with and without DVT than those from healthy controls (p<0.0001)." (PMID 26192925, 2015). "Higher mRNA expression of TNF-α in SAT, not VAT, of cachectic GI cancer patients compared to weight-stable cancer patients was reported in newly diagnosed cancer patients." (PMID 25415607, 2014). "After adjustment for age and gender, the aHR for developing malignancy was 3.14 times higher (95% CI, 1.98 – 4.98, P <0.0001) in children with JIA who had not been exposed to either methotrexate or TNF-alpha inhibitors." (PMID 25174953, 2014). "Unlike TNF-α, TRAIL has been shown to induce apoptosis in cancer cells with minimal cytotoxicity toward non-transformed cells, although under certain circumstances, it enhances the cytotoxicity of several drugs to hepatocytes/liver and mast cells." (PMID 24910845, 2014). "IRF8 has been shown to be a key regulator of Fas-mediated apoptosis in various cancer cells and metastatic phenotypes in CRC cells; however, the correlation between TNF-α-induced apoptosis and IRF8 expression in CRC cells has not been investigated." (PMID 25495942, 2014). "Unlike TNF-α and FasL, TRAIL has been used effectively in systemic animal trials and has the unique feature of inducing apoptosis in cancer cells, whilst sparing normal cells." (PMID 22136382, 2011). "However, whether spinal TNF-α is involved in cancer-induced pain has not been investigated." (PMID 20923560, 2010). "As an expressible peptide, TRAIL has great potential because it is non-toxic to most normal tissues, unlike TNF-α, and because bacterially produced TRAIL has been shown to be cytotoxic to cancer cells." (PMID 19861961, 2009). "Unlike Fas ligand and TNF, TRAIL appears to have limited toxicity for mice and monkeys, suggesting its potential value for cancer therapy." (PMID 15138489, 2004). "Conversely, one must recall that TNF-α can induce apoptosis in cancer cells under certain conditions—however, those conditions (e.g., concentrated regional TNF-α administration) are not representative of the typical systemic TNF-α levels in patients." (PMID 40299527, 2025). "The implementation of a KD intervention in cancer patients did not result in significant changes in the following nine indicators: HDL cholesterol, triglycerides, CRP, IGF-1, TNF-α, creatinine, urea, energy intake, and age at the time of the dietary intervention." (PMID 40756563, 2025).
cancer (continued). "Additionally, BMX-001 reduced TNF-α production in SGCs but not in MDA-MB-231 cells, further supporting its dual role as an antioxidant in normal cells and a pro-oxidant in cancer cells." (PMID 40872550, 2025). "In previous experiments with cancer cell lines, PANoptosis could not be induced by IFN-γ alone, but only by the addition of TNF to IFN-γ." (PMID 40230837, 2025). "Notably, VEGF-A, TNF-α, CCL2, IL-6, and IFN-γ were significantly elevated in the Cancer TIF1-γ-DM group than in the Non-cancer TIF1-γ-DM group." (PMID 36357631, 2023). "This dysregulation is characterized by the upregulation of pathways associated with immune homeostasis, such as inflammation and the nonclassical tumor necrosis factor (TNF)‐mediated nuclear factor‐kappa B signaling pathway, which serves as a pivotal connection between inflammation and cancer." (PMID 38034099, 2023). "This study included both pro‐inflammatory (IL‐1B, IL‐6, IL‐8, IL‐12 (p40, p70), TNF‐α, and IFN‐γ), and anti‐inflammatory (IL‐4, IL‐6, IL‐10, TGF‐β), peripheral cytokine blood serum markers with no significant findings evident between cancer survivors and matched controls." (PMID 37751068, 2023). "The binding of the antibody to this region activates extracellular ERK and JNK pathways, leading to the activation of NF-κB and production of TNF-α which further increases csGRP78 expression in RA-FLS, which unlike the mechanisms observed in cancer, leads the RA cells to apoptosis." (PMID 35740249, 2022). "FC2 induces cancer cell death, and its activity increases with the addition of recombinant TNF (in MDA-MB-231 and SK-OV3) and is not reduced after suppression of autocrine TNF." (PMID 34938412, 2021). "However, owing to the inefficacy of soluble Fas L in apoptosis induction 34 and the systematic toxicity of TNFα 35, potent TRAIL without dose-limited toxicity must be the best choice for combination with PDT in cancer therapy." (PMID 33754061, 2021). "However, our results showed that, according to the present protocol, cancer induction with DMH and/or NFRFP consumption does not modify serum concentrations of IFNγ, IL-6, IL-10, IL-12p70, MCP-1, and TNF-α." (PMID 34444868, 2021). "After TNFα, TRAF3 or GADD45A is knockdown in the HCC cells, both mono-treatments and combination treatment failed to induce apoptosis; and the combination treatment failed to exhibit its synergistic effect in inhibiting the cancer growth." (PMID 34025421, 2021). "Importantly, CIS requires the combined action of TNF and IFN-γ, as immune therapies of cancers in the absence of either IFN-γ, of Stat1- or of Tnfr1-signalling strongly accelerate the transformation and growth of cancer cells." (PMID 32165639, 2020). "Therefore, we here investigated the effects of AIMs in vitro at a lower concentration on Hep3B cells with or without TNF-α, as TNF-α treatments augmented indicates the advanced clinical stage of cancer." (PMID 33233701, 2020). "Tumor necrosis factor (TNF)-related apoptosis-inducing ligand (TRAIL) belongs to the TNF superfamily and has governed particular interest for its ability to preferentially induce apoptosis in cancer cells while sparing surrounding non-transformed cells." (PMID 31146405, 2019). "While TNFα (5 ng ml−1) or phorbol 12-myristate 13-acetate (PMA, 1 nM) induced reactivation of HIV in 2D10 cells 23, cancer cell exosomes failed to stimulate transactivation of the HIV genome, suggesting the unidirectional exosome signaling from HIV-infected T cells to cancer cells." (PMID 30389917, 2018). "These screen results were validated by testing 23 randomly selected cancer cell lines, which showed a complete resistance to TSZ- and TNFα+Cycloheximide+zVAD.fmk (TCZ)-induced necroptosis, lack of RIPK3 expression, and lack of MLKL Ser358 phosphorylation upon stimulation with TSZ treatment." (PMID 30157175, 2018).
cancer (continued). "Moreover, the cytotoxic effect of BSE on cancer cells was significantly reverted by Nec-1 pretreatment, and BSE induced TNF-α and RIP-1 expression in the absence of caspase-8 activity." (PMID 30551590, 2018). "Although TNF-α inhibition has been acknowledged as a potential strategy to prevent CAC, our study suggests that SHH inhibition to target IL-6 is another strategy to either prevent cancer or kill CSCs, which was never achieved before the current investigation." (PMID 26716648, 2016). "When activated with IL-2, NK92 cells were found to have no/low cytotoxicity against NK sensitive cancer stem cells; however, they retained the ability to secrete high levels of regulatory cytokines IL-6 and IL-10 with no or slight secretion of IFN-γ and TNF-α." (PMID 26247631, 2015). "There were 3 cases of incident cancer in the “MTX use, biologics-naïve” group, only 1 in the anti-TNF biologics-containing group and 29 in the “both MTX- and biologics-naïve” group, in comparison, there were 50 cases of cancer in the non-JIA comparator group." (PMID 25174953, 2014). "In the cancer cells, Rb is phosphorylated on CDK2 phosphorylation sites as well as CDK4 phosphorylation sites, whereas our data showed that Rb phosphorylation on the CDK2-specific phosphorylation site, threonine 821, was not induced by TNF-α treatment (day 6)." (PMID 24302570, 2013). "In this study, we also found that AIMs did not prevent completely either TNF-driven EMT or TNF-driven MMP induction, suggesting in TNF-high condition, the efficacy might be limited in HeLa cell-like cancer cells." (PMID 23864892, 2013). "Over a median follow-up period of 4.0 years, the overall incidence of cancers (excluding non-melanoma skin cancer (NMSC)) was greater in patients receiving combined doses of tofacitinib (4.2%; 122 cases) compared to those treated with a TNF inhibitor (2.9%; 42 cases)." (PMID 40507276, 2025). "However, the role of TNF-α and its receptor TNFRs (TNFR1 and 2) and whether they can act as common targets in the development of cancer and SCZ has not been studied." (PMID 38592583, 2024). "KEGG pathway analysis revealed that in both cancers, RCAN1 may be involved positive regulation of cytokine–cytokine regulation, TGF-β signaling, tumor necrosis factor (TNF) signaling, and cell adhesion, and the negative regulation of pyrimidine metabolism, cell cycle, and DNA replication." (PMID 37107558, 2023). "Although KP10 did not impact cancer cell proliferation, KISS1 overexpression and KP10 stimulation reduced TNF-α-induced NF-κB activity and suppressed TNF-α-induced cell migration, respectively, and lowered TNF-α-induced cell attachment to fibronectin in BC cells." (PMID 37970212, 2023). "However, in all DCRGs except THYM, a negative correlation was observed between TMB/MSI and TNF expression, indicating that the treatment strategies for TNYM may differ from other cancers at the level of immune checkpoints." (PMID 37033970, 2023). "Additionally, TNF-α, although not alone, was capable of upregulating MET (receptor for HGF) expression and promoting the antitumor activity of neutrophils in a variety of cancer types." (PMID 32117288, 2020). "In breast cancer, it has been shown that the noncanonical Wnt 5a signaling activation in TAM promoted cancer cell migration through phosphorylation of JNK, followed by an increase in transcription of AP-1/c-Jun and matrix metalloprotease, MMP7, ultimately leads to the secretion of TNF." (PMID 32283687, 2020). "Thirdly, the strong anticancer activity by combination could be significantly inhibited by a TNFα-, but not by a TRAIL- neutralizing antibody, indicating that activation of apoptosis signaling was triggered by TNFα secreted by the cancer cells in an autocrine fashion." (PMID 28460471, 2017).
cancer (continued). "Thus, induction of local production of TNFα may be one way to render cancer cells sensitive to SM, a notion in line with the report that pathogen mimetics generating a cytokine milieu consisting of IFNβ, TNFα and/or TRAIL sensitizes cancer cells to SM." (PMID 27551497, 2016). "Similarly to TNF-α-treated HSMMs, the cytoplasmic translocation of Rb has been shown to be induced by its CDK-mediated phosphorylation in certain types of cancer cells, although the function of cytoplasmic Rb in the cancer cells has not been described thus far." (PMID 24302570, 2013).
inflammation (817 papers, 2005 to 2026). Aberrant reaction of the microcirculation characterized by movement of fluid and leukocytes from the blood into extravascular tissues. "Disruption of this barrier is a hallmark of chronic intestinal inflammation particularly in IBDs, and is primarily driven by pro-inflammatory cytokines, such as TNF-α, IFN-γ, IL-1β, and IL-6." (PMID 42278255, 2026). "The presence of these complexes activates B-cell responses, releases pro-inflammatory cytokines, including TNF-α and IL-6, and finally causes low-grade chronic inflammation throughout the body." (PMID 41473187, 2025). "For instance, in the liver, TNF-alpha causes numerous biological responses including liver inflammation." (PMID 41141269, 2025). "Consistent with previous studies, the current study showed that IFN-γ and TNF-α are secreted by innate immune cells following chronic exposure to PM, suggesting their pivotal role in the associated pathophysiology of pulmonary inflammation." (PMID 40215613, 2025). "Leukocyte counts, C-reactive protein (CRP), interleukin-6 (IL-6), interleukin-10, and tumor necrosis factor-α (TNF-α) are the markers used in most studies that are determined to be associated with low-grade chronic inflammation." (PMID 40332421, 2025). "TLR4 activation leads to increased expression of inflammatory genes such as NF-κB, Myd88, and CD14, resulting in the production of inflammatory cytokines (IL-1β, IL-6, TNF-α), which cause liver inflammation and damage." (PMID 40362886, 2025). "Vascular inflammation, or “inflammaging”, is a hallmark of vascular aging, characterized by elevated pro-inflammatory cytokines such as Tumor Necrosis Factor alpha (TNF-α) and interleukins (IL-1β, IL-6, IL-8, IL-13, IL-18)." (PMID 40944275, 2025). "According to previous reports, inflammatory cytokines such as TNF-α, IL-1β, and IL-6 are closely associated with the occurrence of intestinal inflammation." (PMID 38892496, 2024). "This process leads to the release of pro-inflammatory cytokines (TNF-α, IL-1β, IL-6), which are implicated in airway inflammation." (PMID 39000242, 2024). "Chronic inflammation in the prostate can lead to an overproduction of growth factors, such as tumor necrosis factor-alpha (TNF-α) and interleukin-6 (IL-6), causing excessive prostate cell proliferation and remodeling." (PMID 38519941, 2024). "These AhR ligands play an important role in suppressing the production of pro-inflammatory cytokines like TNF-α and IL-1β, which are implicated in liver inflammation and damage." (PMID 39767818, 2024). "PMOP is strongly associated with systemic chronic inflammation, which is often accompanied by the augmentation of pro-osteoclastogenic factors such as TNF-α and IL-1β." (PMID 38542877, 2024). "We also found that LPS-macrophage EVs primarily activate the TLR, CXCR, and TNF signaling pathways in neutrophils, while inhibiting these pathways reduces lung inflammation and oxidative stress caused by LPS-BMDM-EVs." (PMID 38910259, 2024). "Both TRPV1 and TRPA1, members of the TRP channel superfamily, play a key part in lung inflammation via the release of neuropeptides (substance P) and proinflammatory factors, such as leukotriene, IL-1α, and TNF-α, which cause primary airway inflammation." (PMID 37836429, 2023). "In IBD, the CD is thought to be caused mainly by the Th1 immune response, characterized by IFN-γ, TNF-α, and IL-12-mediated intestinal inflammation, while UC is associated with Th2 response, with IL-5 and IL-13 dominating in inflammation mediation." (PMID 36824689, 2023). "In this study, Duan's research suggested that Pb exposure will cause the occurrence of intestinal inflammation in fish, which was confirmed by the mRNA expression changes in immune-related genes (TNF-α, IL-1β, IL-8, and IL-10)." (PMID 37731918, 2023).
inflammation (continued). "Prolonged P. aeruginosa infections have been linked to chronic inflammation in the CF lung, whose hallmarks are increased levels of cytokines (i.e., TNF-α, IL-1β, IL-6) and neutrophil attraction by chemokines, like IL-8." (PMID 35903151, 2022). "The leading cause of CNS chronic inflammation is the release of inflammatory factors by microglia, such as interleukin-1 (IL-1), interleukin-6 (IL-6), and tumor necrosis factor-α (TNF-α)." (PMID 36570466, 2022). "Oxidative stress causes liver inflammation, leading to secretion of pro-inflammatory cytokines such as TNF-α, interleukin-1 beta (IL-1β) and interleukin-6 (IL-6)." (PMID 36358518, 2022). "IL-8 induces inflammation by mediating low concentrations of TNF-α, which is closely associated with the pathogenesis of intestinal inflammation." (PMID 36107605, 2022). "The consumption of cricket powder was also associated with reduced plasma TNF-alpha, a pro-inflammatory cytokine that has been associated with intestinal inflammation and several inflammatory gut conditions." (PMID 35206005, 2022). "Lack of STAT6 expression in KO mice induced more severe lung inflammation, associated with elevated neutrophil influx and expression of TNF-alpha, IL-6 and IL-1beta in the inflamed lung tissues." (PMID 35606692, 2022). "T2DM can induce liver inflammation evidenced by an increase of proinflammatory cytokines NF-κB, TNF-α, IL-6, and IL-1β, which is associated with cell apoptosis and oxidative stress, all factor promoting HCC progression." (PMID 35002979, 2021). "The increase in intestinal permeability induced by TNF-α, mainly produced by monocyte-macrophages, is considered a significant cause of various intestinal inflammations." (PMID 33535475, 2021). "To address the possibility that the chronic nasal inflammation caused systemic inflammation, we examined the expression levels of representative pro-inflammatory cytokines, TNFα and IL-1β, using serum and spleen extraction by ELISA analysis." (PMID 33633180, 2021). "The central nigrostriatal dopaminergic degeneration followed by bowel inflammation is associated with increased TNF-α and IL-1β." (PMID 32731605, 2020). "Only four strains induced the inflammatory cytokines TNF-α, IL-12(p70), IL-6 and IL-1β, while the remaining Lactobacillus strains downregulated these, which is again reassuring as genital inflammation has been linked to HIV and STI risk." (PMID 32497109, 2020). "To further illuminate the mechanisms that underlie the impact of TNF-α on lung inflammation/injury, we also examined and found mir-331-3p suppressed the expression of inflammation-associated genes MCP-1, VCAM-1, and ICAM-1 in vitro and in vivo." (PMID 33072088, 2020). "A longer duration of CPB goes along with higher risk for renal ischemia and causes renal inflammation by inducing an increase in cytokines such as TNF-α, IL-1 and IL-6." (PMID 29973162, 2018). "TNF-α is a pro-inflammatory cytokine, and increased levels have been associated with intestinal inflammation and several inflammatory gut conditions." (PMID 30018370, 2018). "Chronic inflammation is associated with ageing and characterized by the increased production of pro-inflammatrory mediators such as IL-1β, TNF-α and IL-8 and the activation of NF-кB signaling, as well as infiltration of inflammatory cells." (PMID 30154427, 2018). "Anti-inflammatory therapies like antibodies to TNF and steroids which regulate NF-κB activation are commonly used to treat intestinal inflammation in IBD, but are associated with significant side effects." (PMID 28334039, 2017). "Liver inflammation has been shown to be associated with elevated production of various cytokines such as IL-1β, TNF-α and IFN-γ, which have been implicated in hepatocarcinogenesis." (PMID 28638434, 2017). "CRP, TNF-α, and IL-6, which are a prominent markers of systemic chronic inflammation, have been significantly associated with poor HGS." (PMID 27078883, 2016).